ALKBH5 (alkB homolog 5, RNA demethylase)
Diseases named in the same sentence as ALKBH5 in open-access papers (continued):
Sharing a sentence is not in itself a finding about the gene and the disease.
cancer (continued). "Similarly, ALKBH5 can regulate the m6A methylation level of PTEN mRNA and reduce the stability of PTEN mRNA and promoting the cadmium-induced malignant transformation of human bronchial epithelial cells, as well as enhancing proliferation, migration and invasion of cancer cells." (PMID 38094306, 2023). "However, the biological role of ALKBH5 has not been investigated in pan-cancer datasets." (PMID 35444654, 2022). "Collectively, these data suggest that METTL3, rather than ALKBH5 or METTL4, is responsible for m6A-triggered erastin-induced ferroptosis in cancer cells." (PMID 39800682, 2025).
infection (36 papers, 2017 to 2025). The state of being infected such as from the introduction of a foreign agent such as serum, vaccine, antigenic substance or organism. "Indeed, in vivo infection studies using a mouse model manifested a global increase on cellular m6A levels linked to decreased Alkbh5 mRNA and protein levels, which is mediated by viral NSP1 protein activity." (PMID 36016289, 2022). "Besides, the levels of proinflammatory cytokines interleukin 6 (IL-6) and interleukin 1 beta (IL-1β) were higher during the resolution of infection, in peritoneal cavity or plasma of Alkbh5-deficient mice than WT littermates after a mild CLP." (PMID 35764614, 2022). "Furthermore, infection of U937 cells with m6A-deficient HIV-1 generated from ALKBH5-overexpressed HEK293T cells induced approximately 2-fold higher phosphorylation of IRF3 and IRF7 when compared with control HIV-1." (PMID 33690734, 2021). "A decreased infection burden was detected in IEC 4.1 cells deficient in Alkbh5 or Fto." (PMID 34295340, 2021). "In addition, Alkbh5-deficient septic mice exhibited higher retention of mature neutrophils in the bone marrow and defective neutrophil release into the circulation, which led to fewer neutrophils at the infection site than in their wild-type littermates." (PMID 38114747, 2024). "It has been reported that reduced activity of demethylases like ALKBH5 during infection can lead to excessive methylation, making IFN-related mRNAs unstable and shutting down antiviral defenses." (PMID 40969755, 2025). "Curiously, HCMV infection is also associated with increased levels of the m6A eraser proteins FTO and ALKBH5 late in infection in human fibroblasts." (PMID 39868828, 2025). "Host methyltransferases (METTL3) and demethylases (ALKBH5) regulate these marks dynamically in response to infection." (PMID 40969755, 2025). "Knockdown or inhibition of Alkbh5 in nasal mucosa of mice was mediated by lentiviral infection or IOX1 treatment." (PMID 39011034, 2024). "Immunofluorescence results revealed that both METTL3 and ALKBH5 aggregated in the cytoplasm following infection (Fig. EV1A,C), while METTL14 remained localized in the nucleus before and after infection (Fig. EV1B)." (PMID 39496835, 2024). "The protein level of IL-1β was also upregulated after ALKBH5 knockdown during infections by P. aeruginosa, C. diphtheriae, and the HSV-1 ICP34.5 mutant." (PMID 36625590, 2023). "Similar to the lung tissues, the expression levels of ALKBH5 were significantly up-regulated after infection for 36 h and 48 h." (PMID 35682869, 2022). "In this study, we demonstrate that PEDV can infect porcine lung tissue and the 3D4/21 alveolar macrophage cell line, and the key m6A demethylase ALKBH5 is remarkably induced after PEDV infection." (PMID 35682869, 2022). "We were unable to reproducibly knock-down METTL3, but ALKBH5 was efficiently knocked down after infection with a lentivirus carrying shRNA to ALKBH5." (PMID 35190939, 2022). "During the late stage of infection, higher protein levels of PTGER4 and WNK1 were detected in Alkbh5-deficient neutrophils." (PMID 35764614, 2022). "After revealing that the knockdown of ALKBH5 affected the infection capacity for PEDV, the exact molecular mechanism remained to be explored." (PMID 35682869, 2022). "Nevertheless, 37.61%, 44.89% and 37.41% of the DEDMs were hypermethylated at 2, 4 and 6 h post-infection, respectively, following ALKBH5 knockdown." (PMID 35288544, 2022). "Of interest, upregulated and hypomethylated genes were mostly impacted by ALKBH5 knockdown at a later time point of infection (6 h)." (PMID 35288544, 2022). "Furthermore, knockdown of Alkbh5 expression by lentiviral infection resulted in high MAPK pathway activity and a significant nasal mucosa inflammatory response." (PMID 39011034, 2024). "Therefore, ALKBH5 promotes neutrophil accumulation in the site of infection for bacterial clearance." (PMID 35764614, 2022).
infection (continued). "Therefore, ALKBH5 drives a migration-promoting transcriptional landscape of neutrophils to enable their migration into the site of infection for bacterial eradication." (PMID 35764614, 2022). "Interestingly, the disruption of ALKBH5 expression remarkably increases the infection’s capacity for PEDV." (PMID 35682869, 2022). "Similarly, downregulation of Alkbh5 was previously reported in epithelial cells in response to infection by Streptococcus suis, H1N1 influenza virus, and Chlamydia pneumoniae." (PMID 34295340, 2021). "Moreover, infection of PMA-differentiated U937 cells with HIV-1 from FTO-KO or ALKBH5-KO cells induced approximately 2-fold less IFN-I expression (P <0.005) compared to Ctrl-KO cells." (PMID 33690734, 2021). "Manipulation of Alkbh5 expression levels through the CASPR/Cas9 knock-out and knock-in approach caused reciprocal alterations in global m6A mRNA methylation in host cells, and consequently, infection dynamics of C. parvum in vitro." (PMID 34295340, 2021). "Cells expressing Alkbh5 showed an increase of infection burden." (PMID 34295340, 2021). "However, Alkbh5-deficient mice displayed no changes in peritoneal γδ T cells but reduced numbers of macrophages at later time points of infection." (PMID 38114747, 2024). "Interestingly, our results clearly demonstrate that the disruption of ALKBH5 expression results in an increase in the infection’s capacity for PEDV, suggesting that ALKBH5 may play an important role in restraining PEDV infection." (PMID 35682869, 2022). "Nevertheless, NiV-M infection tended to retain higher residual METTL3 levels and exhibited a greater degree of ALKBH5 suppression compared to NiV-B." (PMID 40573422, 2025). "At different time points post-infection from 0 h to 24 h, WTAP was highly up-regulated at the transcriptional level, accompanied by a slight decrease in demethylase ALKBH5." (PMID 40663568, 2025). "In keeping with these findings, the mRNA levels of METTL3 & METTL14 (m6A writers), ALKBH5 & FTO (m6A erasers), and YTHDF2 (m6A reader) were significantly increased in a time-dependent fashion in Huh7 cells post SFTSV infection." (PMID 39585899, 2024). "The infection also alters the expression of m6A writer (METTL3 and WTAP) and eraser (FTO and ALKBH5) proteins." (PMID 36786625, 2023). "ALKBH5 knockdown increased the levels of p-p38 and p-JNK during infection by P. aeruginosa, C. diphtheriae, WT HSV-1, or the HSV-1 ICP34.5 mutant." (PMID 36625590, 2023). "ALKBH5 knockdown increased the levels of the IL-1β, CSF3, TGM2, and SRC transcripts during infection by P. aeruginosa, C. diphtheriae, WT HSV-1, or the ICP34.5 mutant virus." (PMID 36625590, 2023). "Total RNA extracts isolated from dissociated adult DRG neurons incubated with Act-D for the indicated times (0, 2, 4, and 8 hr) following infection with NC, KD1, and KD2 or control, wt-ALKBH5, and mut-ALKBH5 AAVs for 7 d were subjected to qRT-PCR analyses." (PMID 37535403, 2023). "Immunoblotting with antibodies targeting ALKBH5, FTO, METTL14 and METTL3 in ileum tissue from mice infected with RV EW or treated with PBS was carried out at 2 days post infection (dpi)." (PMID 35098923, 2022). "In accordance with the RNA-seq and qRT-PCR data, deletion of ALKBH5 decreased NLRP12, while increased TNC protein expression in neutrophils during the early stage of infection." (PMID 35764614, 2022). "Using an in vitro infection model employing human intestinal epithelial HCT-8 cells, we further tested the role of ALKBH5-mediated m6A mRNA methylation in human intestinal epithelial anti-C." (PMID 34295340, 2021). "We used siRNA to knockdown either ALKBH5 or FTO in A549 cells and performed a time-course infection with Ad5." (PMID 33243990, 2020). "Depletion of METTL3 or METTL14 enhanced ZIKV infection in 293T cells whereas ALKBH5 and, to a lesser extent, FTO knockdown reduced infection." (PMID 29259584, 2017).
infection (continued). "During infection with DNA viruses, including herpes simplex virus (HSV-1) and monkeypox virus (MPXV), lactylation at K284 of ALKBH5 significantly enhances its binding affinity to interferon-beta (IFN-β) mRNA, thereby promoting the demethylation of its m6A modifications." (PMID 40859309, 2025). "ALKBH5 decreases the stability of NLRP3 mRNA by removing its m6A modification, thereby inhibiting macrophage NLRP3 inflammasome activation and weakening host resistance to infection." (PMID 40859309, 2025). "Notably, ALKBH5 expression showed significant variations between T2 and T3 stages, as well as between patients with HBV+ and HBV− infection." (PMID 38501918, 2024). "ALKBH5 protein was found distributed in both the nucleus and the cytoplasm in uninfected cells, and no changes in distribution were observed after infection." (PMID 36786625, 2023). "Indeed, upon infection, the host m6A machinery, including writers (METTL3-METTL14), erasers (ALKBH5, FTO), and readers (YTHDC1, YTHDF1-3), was found to be upregulated at both the RNA and protein levels." (PMID 36016289, 2022). "After determining that the PEDV copy number significantly decreased after infection for 36 h, we further examined how PEDV infection could be influenced after the disruption of ALKBH5 expression." (PMID 35682869, 2022). "However, METTL3, METTL14, WTAP, ALKBH5, and FTO were all present in both the nucleus and cytoplasm after infection." (PMID 34225491, 2021). "The expression of the demethylase FTO decreased at 48 hpi, whereas that of ALKBH5 was not changed after infection." (PMID 34225491, 2021). "Next, we knocked down ALKBH5 or FTO, or both, in HeLa cells, followed by rgRSV infection." (PMID 31597913, 2019). "In addition, ALKBH5 deletion did not affect the γδ T cell distribution in the peritoneal cavity, the major infection site in mice subjected to CLP, implying that γδ T cells are not responsible for the defective antibacterial defense in Alkbh5-deficient septic mice." (PMID 38114747, 2024). "We noted a slight decrease in METTL3 and METTL14 protein levels at 36 h post-infection (hpi), whereas the protein levels of FTO and ALKBH5 did not significantly change during CVB3 infection." (PMID 39339923, 2024).
bacterial infection (8 papers, 2022 to 2025). "Consistently, significantly decreased surface G-CSFR expression was observed on ALKBH5-deficient dHL-60 human neutrophils upon bacterial infection." (PMID 38114747, 2024). "Therefore, the lower expression of ALKBH5 could be a risk hallmark in bacterial infectious diseases, and also might be associated with impaired antibacterial innate defense." (PMID 35764614, 2022). "During bacterial infection, ALKBH5 imprinted production- and mobilization-promoting transcriptome signatures in both mouse and human neutrophils." (PMID 38114747, 2024). "Altogether, these findings indicate that ALKBH5 is required for the initiation of emergency granulopoiesis during the host response to bacterial infection." (PMID 38114747, 2024). "Collectively, this study proposes a positive role of Alkbh5 in the innate defense against bacterial infection through regulation of intrinsic neutrophil properties, such as polarization in response to stimuli, chemotaxis, and migration." (PMID 37509095, 2023). "N6-methyladenosine (m6A) RNA modification is important in immunity and inflammation, and our preliminary data indicate downregulation of RNA m6A demethylase alkB homolog 5 (ALKBH5) in neutrophils during bacterial infection." (PMID 35764614, 2022). "We found that, at all time points of bacterial infection, >50% of DEDMs had m6A hypomethylation following ALKBH5 knockdown, suggesting an indirect role of ALKBH5." (PMID 35288544, 2022). "As expected, most genes impacted by ALKBH5 knockdown were those upregulated during viral and bacterial infections, or bacterial infection and LPS treatment." (PMID 35288544, 2022). "Furthermore, G-CSFR expression is downregulated in neutrophils upon bacterial infection because of decreased binding of ALKBH5 to the CSF3R mRNA." (PMID 38114747, 2024). "In this study, we demonstrated that ALKBH5 is required for the initiation of emergency granulopoiesis and promotion of neutrophil mobilization in response to bacterial infection by increasing the mRNA stability and protein expression of the G-CSF receptor in both mouse and human neutrophils." (PMID 38114747, 2024). "Moreover, deletion of ALKBH5 significantly decreased the level of CSF3R mRNA in dHL-60 human neutrophils upon bacterial infection and LPS stimulation." (PMID 38114747, 2024). "Interestingly, the amount of ALKBH5 bound to the CSF3R mRNA was lower during bacterial infection than under physiological conditions." (PMID 38114747, 2024). "This suggests that Alkbh5 is involved in the host defense against bacterial infection." (PMID 37509095, 2023). "Inspired by our preliminary observation on the downregulation of ALKBH5 in neutrophils during bacterial infection, in this study, we investigated the roles of ALKBH5 and m6A RNA modification in intrinsically regulating neutrophil behavior in antibacterial innate defense." (PMID 35764614, 2022). "Nevertheless, a consistent fraction of the upregulated and hypermethylated genes (15–35%) at all the time points during bacterial infection were indeed downregulated following ALKBH5 knockdown, suggesting a negative regulatory role of m6A hypermethylation for these genes." (PMID 35288544, 2022). "Firstly, we analyzed the expression of ALKBH5 and other m6A modulators during bacterial infection." (PMID 35764614, 2022). "Importantly, we found that most enriched pathways of DMs were related to immune responses, further confirming the regulation of immune response by ALKBH5 during bacterial infection." (PMID 35288544, 2022). "However, 30.58%, 26.32% and 21.77% of these genes were upregulated while 19.57%, 18.58% and 24.15% of them were downregulated following ALKBH5 knockdown when presented by 2, 4 and 6 h following bacterial infection, respectively." (PMID 35288544, 2022). "The RNA-seq data showed that ALKBH5 deletion significantly decreased the transcript level of CSF3R in both mouse and human neutrophils upon bacterial infection." (PMID 38114747, 2024).
bacterial infection (continued). "The RIP-qPCR results confirmed the direct binding of ALKBH5 to the CSF3R mRNA, and the binding strength declined upon bacterial infection, accounting for the decrease in G-CSFR expression on bacteria-infected neutrophils." (PMID 38114747, 2024). "Secondly, there are almost 4 times more DMs than DEs during bacterial infection following ALKBH5 knockdown, indicating that m6A alterations do not always lead to differential gene expression." (PMID 35288544, 2022).
metabolic disease (6 papers, 2022 to 2026). A congenital disorder (due to inherited enzyme abnormality) or acquired (due to failure of a metabolically important organ) disorder resulting from an abnormal metabolic process. "Overall, ALKBH5 emerges as a key epitranscriptomic regulator in metabolic diseases, and advancing therapeutic strategies that account for molecular context and tissue specificity will be critical for achieving safe and effective clinical interventions." (PMID 42072621, 2026). "A growing body of recent studies has focused on the relationship between ALKBH5 and metabolic diseases, revealing that ALKBH5 plays a major role in glucolipid metabolism and metabolic disorders by regulating relevant genes and signaling pathways." (PMID 40001461, 2025). "By integrating mechanistic discovery with translational strategy, our findings lay the groundwork for developing ALKBH5‐based diagnostics and therapies, with broader implications for RNA methylation‐targeted interventions in neurodegenerative and metabolic diseases." (PMID 40548888, 2025). "However, the role of ALKBH5 in metabolic disorders, especially T2DM, remains controversial." (PMID 40001461, 2025).
cardiovascular diseases (5 papers, 2021 to 2025). "The m6A demethylase ALKBH5 is reported to be associated with cardiovascular diseases, whereas the functional role of ALKBH5 in cardiomyocyte hypertrophy remains confused." (PMID 39294131, 2024). "Notably, ALKBH5 has also been implicated in cardiovascular diseases." (PMID 40186131, 2025). "Subsequent studies identified aberrant ALKBH5 expression plays a vital part in the pathogenesis of several cardiovascular diseases, such as aortic dissection, and post-ischemic angiogenesis." (PMID 39294131, 2024). "Since that time, m6A methylation has been extensively studied, and its functions, mechanisms, and effectors (e.g., METTL3, FTO, METTL14, WTAP, ALKBH5, and YTHDFs) in various diseases, including cardiovascular diseases, have rapidly been investigated." (PMID 34221238, 2021). "In recent years, many studies have revealed the critical roles of m6A methylation in cardiovascular diseases, which were exemplified by abnormal levels of m6A modification as a result of methyltransferases (writer, Mettl3, and Mettl14) and demethylases (eraser, ALKBH5, and FTO)." (PMID 35004673, 2021).
reproductive system diseases (3 papers, 2020 to 2025). "The close relationship between ALKBH5 and the occurrence and development of reproductive system disorders, including reproductive system cancers, germ cell development, and abortion, has attracted increasing attention." (PMID 40001461, 2025). "For example, ALKBH5 acted to influence spermatogenesis and trophoblast invasion, thus affecting human reproductive system diseases." (PMID 32742194, 2020). "Interestingly, ALKBH5, a primary m6A demethylase, not only plays a key role in human reproductive system diseases, but is also believed to be directly regulated by HIF‐1α under hypoxia." (PMID 38344897, 2024).
adenocarcinoma (2 papers, 2023 to 2025). A common cancer characterized by the presence of malignant glandular cells. "Moreover, ALKBH5 cKO mice had reduced the incidence of adenocarcinoma and HGD (P < 0.0001) and suppressed cell proliferation." (PMID 41390849, 2025).
heart disease (2 papers, 2021 to 2024). "ALKBH5 is a well-known m6A demethylase and plays a critical role in human diseases including heart disease." (PMID 35127873, 2021).
hematological malignancies (2 papers, 2019 to 2021). "From the analysis on the “Total” data set IGF2BP1, ALKBH5, IGF2BP2, RBM15, METTL3, ZNF217 is the potentially carcinogenic gene in hematological malignancies." (PMID 33816257, 2021).
immune diseases (2 papers, 2024 to 2025). "ALKBH5, an important modifier of m6A methylation, has been reported in other immune diseases." (PMID 39011034, 2024).
neurodegenerative disease (2 papers, 2023 to 2025). A disorder of the central nervous system characterized by gradual and progressive loss of neural tissue and neurologic function. "ALKBH5 is mainly localized in nuclear speckles and has been shown to have a crucial role in both neurodevelopmental and neurodegenerative diseases." (PMID 37385994, 2023). "ALKBH5 has a crucial role in both neurodevelopment and neurodegenerative diseases." (PMID 37385994, 2023).
blood cancers (1 paper, 2022). "Unlike ALKBH5, FTO expression in MM was not high compared with other blood cancers and solid tumors." (PMID 34759347, 2022).